KLF16 (KLF transcription factor 16)
Description:
Transcription factor that binds GC and GT boxes and displaces Sp1 and Sp3 from these sequences. Modulates dopaminergic transmission in the brain (By similarity).
Synonyms: BTEB4; NSLP2; DRRF
Tractability: PROTAC: its protein half-life has been measured.
Gene: Protein-coding gene on chromosome 19 (1,852,399 to 1,863,579, reverse strand). Ensembl gene ENSG00000129911.
Subcellular location: Nucleus
Subcellular location (Human Protein Atlas): Nucleoplasm
Pathways (Reactome):
Signal Transduction: TGFBR3 expression
Gene Ontology:
Molecular function: protein binding; sequence-specific double-stranded DNA binding; DNA-binding transcription factor activity, RNA polymerase II-specific; RNA polymerase II cis-regulatory region sequence-specific DNA binding; DNA binding; DNA-binding transcription factor activity; DNA-binding transcription repressor activity, RNA polymerase II-specific
Biological process: regulation of transcription by RNA polymerase II; negative regulation of transcription by RNA polymerase II
Cellular component: nucleoplasm; chromatin; nucleus
Genetic constraint (gnomAD): Loss-of-function variants: 6 observed, 4.09 expected, observed/expected ratio (o/e) 1.47, 90% interval 0.74 to 1.93. That is too few expected variants to judge how well the gene tolerates losing a copy. Missense variants: 355 observed, 262.15 expected, observed/expected ratio (o/e) 1.35, 90% interval 1.24 to 1.48. Synonymous variants: 211 observed, 136.33 expected, observed/expected ratio (o/e) 1.55, 90% interval 1.38 to 1.74.
Homologues: Orthologues: macaque KLF16 (99% identical), dog KLF16 (94% identical), pig KLF16 (91% identical), mouse Klf16 (88% identical), zebrafish klf13 (43% identical), zebrafish zgc:153115 (41% identical), Drosophila melanogaster luna (23% identical). Paralogues in human: KLF14 (55% identical), KLF13 (48% identical), KLF11 (35% identical), KLF9 (35% identical), KLF10 (33% identical), SP9 (30% identical), SP8 (30% identical), SP7 (29% identical), SP5 (28% identical), KLF5 (27% identical), KLF12 (26% identical), KLF15 (25% identical), and 10 more.
Diseases named in the same sentence as KLF16 in open-access papers:
KLF16 is named in the same sentence as 21 diseases in open-access papers, as found by Europe PMC text mining. Sharing a sentence is not in itself a finding about the gene and the disease. The quoted sentences say what the papers report.
glioma (6 papers, 2019 to 2026). A benign or malignant brain and spinal cord tumor that arises from glial cells (astrocytes, oligodendrocytes, ependymal cells). "A specific and direct binding of KLF16 to the BTE region in TFAM promoter has been demonstrated by chromatin immunoprecipitation assay in glioma cells." (PMID 41424862, 2026). "The expression of KLF16 was found to be robustly reduced in six glioma cell lines and glioma tissues via Western blot studies and real-time PCR analysis." (PMID 37332990, 2023). "In patients with glioma, KLF16 serves as a key regulator of glioma cell proliferation by binding to the TFAM promoter, leading to the reduction of TFAM expression." (PMID 32824374, 2020). "Prognosis of disease development was also negatively affected with lower mtDNA copy number in esophageal squamous cell carcinoma and with low expression of KLF16 in glioma cells." (PMID 32824374, 2020). "LINC00599 has been found to inhibit glioma cell proliferation and promote cell apoptosis through modulating miR-185-5p/KLF16 axis." (PMID 30867254, 2019). "Furthermore, survival analysis showed glioma patients with low KLF16 had a poor prognosis (HR = 2.328, 95% CI = 1.387–4.017, p < 0.01)." (PMID 37332990, 2023).
lung carcinoma (5 papers, 2022 to 2025). "Among several targets, the human LMNB2 gene, which locates in chromosome 19p13.3 and encodes a 68-kDa protein, was a potential target for KLF16 in lung cancer development." (PMID 35387557, 2022). "Since KLF16 acts as an important transcription factor, to explore how KLF16 functions as an oncogene in lung cancer, the potential targets of KLF16 in lung cancer were determined." (PMID 35387557, 2022). "This study aimed to explore the function and molecular mechanism of KLF16 in lung cancer development." (PMID 35387557, 2022). "In conclusion, KLF16 can be used as a potential therapeutic and preventive biomarker in lung cancer treatment and prognosis by actively regulating the expression of LMNB2." (PMID 35387557, 2022). "Gain-of-function and loss-of-function experiments were performed to explore the in vitro and in vivo function of KLF16 in lung cancer cells." (PMID 35387557, 2022). "In addition to KLF1, KLF13, KLF14 and KLF16 or KLF18 (?)with machine learning prediction waiting for verification, many KLFs have been found to be associated with the progress of lung cancer by activating or inhibiting target gene expression." (PMID 38560274, 2024). "KLF16 overexpression promoted lung cancer cell growth and invasion." (PMID 37491302, 2023). "We suspected that KLF16 acted as an oncogene in lung cancer development." (PMID 35387557, 2022). "KLF16 downregulation inhibited lung cancer cell proliferation and migration." (PMID 35387557, 2022). "In this study, KLF16 was overexpressed in lung cancer samples." (PMID 35387557, 2022). "In this study, we hypothesized that KLF16 might act as an oncogene in the development of lung cancer." (PMID 35387557, 2022). "A luciferase reporter assay was performed to verify the correlation between LMNB2 and KLF16, and the results showed that KLF16 might transcriptionally regulate LMNB2 expression in lung cancer." (PMID 35387557, 2022). "In summary, KLF16 acts as an oncogene in lung cancer by regulating the expression of LMNB2." (PMID 35387557, 2022). "Herein, we confirmed that KLF16 is an oncogene that is involved in the development of lung cancer." (PMID 35387557, 2022). "Conversely, KLF16 overexpression promoted lung cancer cell growth and invasion." (PMID 35387557, 2022). "Thus, the present study aimed to investigate the clinical significance, cellular function, and downstream effector of KLF16 in lung cancer." (PMID 35387557, 2022). "However, up to now, whether some KLFs (KLF1, KLF13, KLF14 and KLF16) with unknown functions are involved in the progressions of lung cancer have not been fully understood, and remain to be explored or verified at the levels of cell, tissue and animal models." (PMID 38560274, 2024). "Next, we investigated whether KLF16 promoted lung cancer progression through LMNB2." (PMID 35387557, 2022). "In lung adenocarcinoma, KLF16 enhances the transcription activity of LMNB2 and promotes lung cancer cell growth and invasion." (PMID 40366008, 2025). "Among the 20E-down-regulated genes in lung cancer cells, several of them are considered to be oncogenes, including Notch3, HSF1, mTOR, SOX12, KLF16 (Kruppel-like factor 16,), and others." (PMID 37233697, 2023). "However, the role of KLF16 in the development of lung cancer remains unknown." (PMID 35387557, 2022). "However, the exact role of KLF16 in lung cancer remains unclear." (PMID 35387557, 2022). "Furthermore, qRT-PCR, immunoblotting, luciferase reporter and rescue assays were carried out to investigate the relationship between KLF16 and LMNB2 in lung cancer cell growth, migration and tumorigenesis." (PMID 35387557, 2022). "Here, a positive correlation was found between KLF16 and LMNB2 in lung cancer tissues." (PMID 35387557, 2022). "Our study illustrates the mechanism of KLF16 in lung cancer progression-positive regulation of LMNB2 expression and suggests that LMNB2 level may serve as an indicator of prognosis for patients with lung cancer." (PMID 35387557, 2022).
lung carcinoma (continued). "However, no study has reported the KLF16 expression in lung cancer." (PMID 35387557, 2022). "Although our study illustrated a story that KLF16 upregulated LMNB2 to promote the growth, proliferation, migration and tumorigenesis of lung cancer cells, whether other proteins participate in KLF16 driving lung cancer development should be determined in the future." (PMID 35387557, 2022).
breast carcinoma (3 papers, 2022 to 2023). "In addition, several lines of evidence indicate that KLF16 is implicated in a variety of tumor processes, including prostate cancer, breast cancer, bladder cancer, gastric cancer and lung cancer." (PMID 36639679, 2023). "KLF16 expression was much greater in breast cancer tissues than in normal tissues, and knocking down KLF16 greatly reduced cell proliferation in vitro and in vivo." (PMID 35345512, 2022). "Furthermore, KLF16 overexpression promotes migration and invasion of breast cancer cells by facilitating EMT." (PMID 36639679, 2023).
gastric cancer (3 papers, 2022 to 2023). A primary or metastatic malignant neoplasm involving the stomach. "The expression level of KLF16 suggests lymph node status and the possibility of distant metastases in gastric cancer tissue." (PMID 36761967, 2023). "KLF16, on the other hand, is overexpressed in gastric cancer and promotes cancer cell growth and metastasis by activating the NOTCH pathway." (PMID 36761967, 2023). "The overexpression of KLF16 can be used to distinguish lung and gastric cancer from nontumor tissues." (PMID 36761967, 2023). "In addition, studies has shown that genes such as RN181, KLF16 and PCAF were involved in the progress of gastric cancer by regulating CDK4 levels." (PMID 35494047, 2022).
bladder cancer (2 papers, 2024). "Elevated expression of KLF16 was observed in bladder cancer tissues, and higher expression levels of KLF16 were correlated with poor progression-free survival (PFS) and cancer-specific survival (CSS) probabilities in BLCA patients." (PMID 39551759, 2024). "The biological functions of KLF16 in bladder cancer were investigated both in vitro and in vivo." (PMID 39551759, 2024). "The clinical relevance of KLF16 and MYC in bladder cancer was evaluated through analyses of public databases and immunohistochemistry." (PMID 39551759, 2024). "In urinary bladder cancer, STIL contributes to cell proliferation by inhibiting primary cilia formation through its interaction with AURKA, while in triple-negative breast cancer, it promotes malignancy by activating the Fanconi anemia pathway through KLF16 interactions." (PMID 39727708, 2024).
glioblastoma (2 papers, 2023 to 2025). The most malignant astrocytic tumor (WHO grade IV). "Although KLF16 is known for its roles in glioblastoma and colorectal carcinomas, its specific function in glycolipid metabolism remains poorly understood, although it has been noted to mitigate fatty liver inflammation by targeting PPARα." (PMID 41031795, 2025). "In glioblastoma, lncRNA RNCR3 can increase KLF16 expression by inhibiting miR-185-5p, and KLF16 acts as a direct target of this regulatory axis to induce apoptosis." (PMID 36761967, 2023). "However, for Krüppel-like factor 16(KLF16), the main member of this family, current literature reports are limited to the role of KLF16 in the occurrence and development of glioblastoma, colorectal carcinomas, and other tumors." (PMID 41031795, 2025).
Insulin resistance (2 papers, 2021 to 2023). Increased resistance towards insulin, that is, diminished effectiveness of insulin in reducing blood glucose levels. "In non-alcoholic fatty liver disease (NAFLD), KLF16 improves steatohepatitis and insulin resistance by targeting PPARα." (PMID 37391422, 2023).
lung adenocarcinoma (2 papers, 2022 to 2025). A carcinoma that arises from the lung and is characterized by the presence of malignant glandular epithelial cells. "The upregulation of KLF16 and LMNB2 was observed in lung adenocarcinoma samples, which accelerated the proliferation and invasion of H1299 and H1975 cells." (PMID 35387557, 2022).
myocardial ischemia (2 papers, 2021 to 2022). A disorder of cardiac function caused by insufficient blood flow to the muscle tissue of the heart. "In conclusion, the results from this study demonstrate that KLF16 reduced oxidative stress and inflammation, and presented MI in vivo model of myocardial ischemia-reperfusion through the induction of PPARβ by TFAM." (PMID 34823421, 2021). "Immunofluorescence showed that the over-expression of KLF16 suppressed TFAM expression in vitro model of myocardial ischemia-reperfusion." (PMID 34823421, 2021). "Next, this study used KLF16 plasmid or si-KLF16 mimics to regulate KLF16 expression in vitro model of myocardial ischemia-reperfusion." (PMID 34823421, 2021). "Here, we showed TFAM/PPARβ signal passage is target spot of KLF16 in Myocardial ischemia-reperfusion." (PMID 34823421, 2021). "In order to elucidate the function of KLF16 in vivo and vitro models of myocardial ischemia-reperfusion, human KLF16 recombinant protein or anti-KLF16 body was injected into mice with myocardial ischemia-reperfusion." (PMID 34823421, 2021). "The inhibition of KLF16 reduced oxidative stress and inflammation, and presented myocardial ischemia (MI) in vivo model of myocardial ischemia-reperfusion." (PMID 34823421, 2021). "Collectively, these data indicated that KLF16 reduced oxidative stress and inflammation to present myocardial ischemia-reperfusion by TFAM/PPARβ signal passage." (PMID 34823421, 2021). "Serum mRNA of KLF16 was positive correlation with serum creatine kinase MB (CK-MB) or creatine kinase (CK) levels in patients with myocardial ischemia-reperfusion." (PMID 34823421, 2021). "In the present study, KLF16 reduced oxidative stress and inflammation, and presented MI in vivo model of myocardial ischemia-reperfusion." (PMID 34823421, 2021). "This study is aimed at investigating mechanisms and effects of Krüppel-like factor 16 (KLF16) affects myocardial ischemia-reperfusion." (PMID 34823421, 2021). "The assessed the role of TFAM involved in the function of KLF16 in myocardial ischemia-reperfusion by interacting with its promoter." (PMID 34823421, 2021). "Then these results of qRT-PCR revealed that serum KLF16 mRNA expression was more effectively increased in myocardial ischemia-reperfusion." (PMID 34823421, 2021). "This study is aimed at investigating mechanisms and effects of KLF16 affects myocardial ischemia-reperfusion." (PMID 34823421, 2021). "At the same time, si-KLF16 mimics reduced KLF16 expression in vitro model of myocardial ischemia-reperfusion." (PMID 34823421, 2021). "For the firstly time, we initially found that the expression of KLF16 mRNA and protein in patients or mice with myocardial ischemia-reperfusion were also increased." (PMID 34823421, 2021). "The expression of KLF16 mRNA in mice with myocardial ischemia-reperfusion was up-regulated at time dependence." (PMID 34823421, 2021). "In general, KLF16 is identified to be highly expressed in model of myocardial ischemia-reperfusion." (PMID 34823421, 2021). "PPARβ promoter region KLF16 affects myocardial ischemia-reperfusion." (PMID 34823421, 2021). "The study further assessed that the role of TFAM in KLF16 affects myocardial ischemia-reperfusion." (PMID 34823421, 2021). "KLF16 plays a key role in the maintenance of myocardial ischemia-reperfusion and KLF16 may alleviate oxidative stress and inflammation by activation of TFAM/PPARβ signaling pathway." (PMID 34823421, 2021). "Serum KLF16 mRNA expression was increased in myocardial ischemia-reperfusion." (PMID 34823421, 2021). "knock-out KLF16 reduced oxidative stress and inflammation of myocardial ischemia-reperfusion." (PMID 34823421, 2021). "KLF16 plasmid increased KLF16 expression in vitro model of myocardial ischemia-reperfusion." (PMID 34823421, 2021). "TFAM participate in KLF16 affects myocardial ischemia-reperfusion." (PMID 34823421, 2021). "The expression of KLF16 protein in mice with myocardial ischemia-reperfusion was also increased." (PMID 34823421, 2021).
myocardial ischemia (continued). "Thus, this study suggests that KLF16 may provide a novel therapeutic strategy for myocardial ischemia-reperfusion." (PMID 34823421, 2021). "Besides, we validated that KLF16 could increase oxidative stress and inflammation in model of myocardial ischemia-reperfusion." (PMID 34823421, 2021). "KLF16 may provide a novel therapeutic strategy for myocardial ischemia-reperfusion." (PMID 34823421, 2021). "KLF16, also known as BTEB4 or NSLP2, is an important regulator involving in the progression of myocardial ischemia-reperfusion." (PMID 35387557, 2022). "Human KLF16 recombinant protein induced PPARβ protein expression, and suppressed TFAM protein expression in heart tissue of mice with myocardial ischemia-reperfusion." (PMID 34823421, 2021). "Meanwhile, over-expression of KLF16 not only induced PPARβ and KLF16 protein expressions, but also suppressed TFAM protein expression in vitro model of myocardial ischemia-reperfusion." (PMID 34823421, 2021). "Apart from that, the down-regulation of KLF16 suppressed PPARβ and KLF16 protein expressions, and induced TFAM protein expression in vitro model of myocardial ischemia-reperfusion." (PMID 34823421, 2021). "Anti-KLF16 body suppressed PPARβ protein expression and induced TFAM protein expression in heart tissue of mice with myocardial ischemia-reperfusion." (PMID 34823421, 2021). "Taken together, our results indicated that KLF16 suppressed TFAM expression, leading to oxidative stress and inflammation in model of myocardial ischemia-reperfusion." (PMID 34823421, 2021). "Serum mRNA of KLF16 was negative correlation with serum TFAM mRNA expression in patients with myocardial ischemia-reperfusion." (PMID 34823421, 2021).
endometriosis (1 paper, 2024). The growth of functional endometrial tissue in anatomic sites outside the uterine body. "Furthermore, multiple studies have discovered that KLF9, KLF11, KLF12, KLF15, and KLF16 are all involved in the occurrence and development of endometriosis." (PMID 39263604, 2024).
liver fibrosis (1 paper, 2026). "Collectively, these results indicate that macrophage Nrf1-Foxo1 interaction regulates its target gene KLF16, which may be involved in energy imbalance and subsequent liver fibrosis." (PMID 41424862, 2026).
oral squamous cell carcinoma (1 paper, 2023). "KLF16 expression was upregulated in oral squamous cell carcinoma, and interfering with KLF16 led to cell cycle arrest, inhibited tumor cell growth, and promoted cell apoptosis." (PMID 36761967, 2023).